TET1 (tet methylcytosine dioxygenase 1)
Diseases named in the same sentence as TET1 in open-access papers (continued):
Sharing a sentence is not in itself a finding about the gene and the disease.
breast cancer (continued). "The noted repression of TET1 expression in breast cancer correlates with NF-κB signaling and infiltration of immune cells in breast cancer; in addition to the recruitment of p65/RelA onto its consensus elements within the TET1 promoter in breast cancer cells." (PMID 31426393, 2019). "Recent data suggest that TET1 transcription is repressed by the NF-κB pathway and modified by the immune system in basal-like breast cancer." (PMID 31426393, 2019). "The methylation/demethylation cycle was assessed in the breast cancer cells and tumorspheres through mRNA expression of DNMT3a, 3b, and TET1,2,3." (PMID 30915120, 2019). "Vitamin C counteracts miR-302/367 to suppress breast cancer stem cell reprogramming via decreasing TET1 gene expression." (PMID 30688660, 2019). "Chromatin remodeling factor, HMGA2 downregulation has been shown to stimulate TET1’s expression in breast cancer cells." (PMID 31426393, 2019). "It has been revealed that multiple HOXA genes were involved in promoting invasion in breast cancer cells through the HMGA2/TET1/HOXA signaling pathway." (PMID 31013831, 2019). "High TET1 expression is related to lower infiltration by immune cells, such as T and B cells, in basal-like breast cancer." (PMID 31022963, 2019). "Although OGT is known to be upregulated in breast cancer, its relationship with TET1 function in female cancer remains undefined." (PMID 31426393, 2019). "TET1, which was expressed at a very low level, was slightly downregulated (0.67 fold) in 42.5% of breast cancer cases." (PMID 29593282, 2018). "It has been shown that overexpression of TET1 can partially re-establish a normal 5hmC profile in breast cancer cells and decrease their invasiveness." (PMID 29593282, 2018). "Restoring 5hmC levels by overexpressing TET2 in melanoma cells, TET1 in breast cancer cells, and IDH1 in renal cancer cells demonstrated inhibitory effects in vitro and in vivo." (PMID 30005692, 2018). "This study helps to delineate a complex signaling network in breast cancer mediated by miR-29b and presents a miR-29b/TET1/ZEB2 pathway involved in the progression of breast cancer." (PMID 29254230, 2017). "In breast cancer, TET1 suppresses tumor growth, intravasation, and metastasis dependent of its catalytic activity." (PMID 27557497, 2016). "TET1 downregulation is found in prostate and breast cancer tissues, which facilitates tumor growth, cell invasion and metastasis." (PMID 26861406, 2016). "And in breast cancer, TET1 maintained expression of tissue inhibitors of metalloproteinases, which blocked activity of MMPs, inhibited vascular invasion." (PMID 27121319, 2016). "Further more, Hsu demonstrated the inhibition of the invasiveness of breast cancer cells by TET1 in vivo and that down-regulation of TET1 expression in patients with breast cancer correlates with poor survival." (PMID 26207381, 2015). "In this present study, we further analyzed the association between the expression of mRNAs encoding TET1–3 and TDG with the prognosis of breast cancer patients." (PMID 26207381, 2015). "A recent study showed that TET1 expression is negatively regulated by CpG methylation near the TSS in breast cancer cells and T-cell acute lymphoblastic leukemia cell lines." (PMID 26462176, 2015). "Hsu reported that TET1 mRNA expression correlates inversely with the survival of patients with breast cancer patient and that down-regulation of TET expression correlates positively correlated with larger tumor size and advanced stage." (PMID 26207381, 2015). "In summary, our study demonstrates that patients with breast cancer with high levels of TET1 mRNA had better OS than those with low expression of TET1 and that TNM stage was a prognostic factor." (PMID 26207381, 2015). "Expression of mRNAs encoding TET1–3 and TDG in 162 breast cancer tissues was quantified using real-time polymerase chain reaction analysis." (PMID 26207381, 2015).
breast cancer (continued). "Published studies have shown that overexpressing TET2 in melanoma cells and TET1 in breast cancer cells increases their 5hmC content and decreases their malignancy in vitro and in vivo." (PMID 25977731, 2015). "Their findings suggested that nuclear factor-kappa B (NF-kB) activation could suppress TET1 via p65 binding, with low TET1 expression correlating with elevated immune markers in basal-like breast cancer tissues." (PMID 40520993, 2025). "Additionally, some studies have reported TET1 as a tumor suppressor gene in breast cancer, but it also exhibits oncogenic properties in other breast cancer studies." (PMID 40599235, 2025). "Subsequent studies have further highlighted TET1's role in breast cancer." (PMID 40520993, 2025). "This study aimed to elucidate the molecular mechanisms through which the TET1/SMAD4/GATA6 regulatory axis governs CAF activation in breast cancer, focusing on its role in sustaining TGF-β signaling, promoting stromal-tumor crosstalk, and driving tumor progression." (PMID 40216762, 2025). "Additionally, Collignon et al35 uncovered a novel immune-related mechanism for TET1 regulation in basal-like breast cancer." (PMID 40520993, 2025). "The study revealed that reduced TET1 levels hindered hydroxymethylation of the AJAP1 (adherens junctions associated protein 1) promoter, thereby activating β-catenin signaling and promoting urinary breast cancer development." (PMID 40520993, 2025). "In addition, although hypoxia reduces TET enzymatic activity in cancer cells, hypoxia-induced increase of the 5-hmC level locally in the genomic region containing TNF-α gene of breast cancer cells is mediated by TET1 and TET3." (PMID 40764968, 2025). "Furthermore, metastatic breast cancer tissues and cell lines (including MDA-MB-231) exhibit lower TET1 expression compared to non-invasive breast cancer samples and cell lines (including SkBr3)." (PMID 39201247, 2024). "However, in our study, tamoxifen derivatives appeared to have the least impact on TET1 in breast cancer cells." (PMID 39201247, 2024). "These limitations can lead to immature conclusions about TET1 isoform roles in breast cancer, especially in light the fact that different TET1 isoforms might have different functions, expression patterns and cellular localization." (PMID 35646706, 2022). "We hypothesized that TET1 isoforms have different expression patterns, localization and regulation in different types of breast cancer." (PMID 35646706, 2022). "In addition, TET1 was shown to be overexpressed in basal like breast cancer samples and that its level negatively correlates with immune defense mechanisms that are related to NF-kB signaling pathway." (PMID 35646706, 2022). "Therefore, we focused on the regulation of TET1 on DNA demethylation and protein expression of breast cancer tumor suppressor genes." (PMID 35978806, 2022). "In addition to TET1, we report here that TET3 is also associated with a global loss of 5-hmC in breast cancer." (PMID 36230901, 2022). "For example, TET1 promoter is methylated in different types of cancers, including breast cancer." (PMID 35646706, 2022). "In prostate and breast cancers, TET1 transactivates TIMP2 and TIMP3 to inhibit cancer invasion." (PMID 35805009, 2022). "Thus, to further shed light on the correlation between tumor subtype and TET1 isoform expression pattern, we tested the expression level of TET1 isoforms in basal and luminal breast cancer animal models." (PMID 35646706, 2022). "In breast cancer, TET1 has been identified as both a tumor suppressor as well as an oncogene." (PMID 35646706, 2022). "In breast cancer, TET1 was shown to play controversial roles." (PMID 35646706, 2022). "To prove our hypothesis, we studied the expression of TET1 isoforms in basal and luminal breast cancer cell lines, as well as in basal and luminal breast cancer animal models." (PMID 35646706, 2022).
breast cancer (continued). "Moreover, the TET1 expression level was inversely correlated with breast cancer cell invasion and tumor development." (PMID 34885145, 2021). "Moreover, during the progression from ductal carcinoma in situ (DCIS) to invasive ductal carcinoma (IDC) in breast cancer, the nuclear expression of TET1 and TET2 decreased significantly, accompanied by a reduction in global DNA 5hmC level." (PMID 33716151, 2021). "Hence, it is necessary to fully consider different subtypes of breast cancer when exploring therapeutic targets for breast cancer based on the suppressive effect of TET1 on related genes." (PMID 34656178, 2021). "Furthermore, analysis of the raw RNAseq data for breast cancer from the TCGA database revealed expression from this alternate promoter in many TNBC cases suggesting that TET1 overexpression in TNBC cases is partly driven by activation of TET1ALT promoter." (PMID 34209564, 2021). "Tao and colleagues found that EZH2 inhibitors could reactivate TET1 expression in basal-like breast cancer cell lines, indicating that TET1 gene might be epigenetically repressed by H3K27me3 in basal-like breast cancer." (PMID 34885145, 2021). "Therefore, together these findings first support the fact that in certain TNBCs when TET1 is high, immune response genes are low, and in other basal-like breast cancers, TET1 is low possibly because of immune system modulating the cancer cell epigenetics." (PMID 34209564, 2021). "Dysregulation of TET1 expression or function and aberrant methylation have been observed in a wide range of cancers, for example, gastric cancer, thyroid carcinoma, lung cancer, gliomas, esophageal carcinoma, and breast cancer." (PMID 34844636, 2021). "It was found that 5hmC levels were positively correlated with the expression levels of TET proteins, especially TET1 (r = 0.5719, P < 0.0001), suggesting that TET1 may play a dominant role in regulating the 5hmC levels during breast cancer metastasis." (PMID 33716151, 2021). "The upregulation of TET1 has attenuated the proliferation and migration of breast cancer cells." (PMID 34804971, 2021). "TET1 is downregulated in prostate and breast cancer tissues." (PMID 32089682, 2020). "Furthermore, it has been reported that the levels of TET enzymes are significantly reduced in breast cancer, in particular the levels of TET1." (PMID 33182353, 2020). "Interestingly, TET1 itself appears to be also a target of DNA methylation epigenetic silencing, in cervical and breast cancers." (PMID 31426393, 2019). "The expression of TET1 or HOXA9 significantly reduced the bone metastasis of breast cancer cells." (PMID 31013831, 2019). "Furthermore, HMGA2 depletion in breast cancer cells resulted in downregulation of miR-29 and induction of its target TET1, which in turn demethylates the promoter of the metastasis-suppressor HOXA9 and promotes its transcription." (PMID 30149591, 2018). "When HMGA2 was depleted by siRNA in breast cancer cells, an up-regulation of TET1 was noted." (PMID 28587163, 2017). "TET1 inhibition with siRNA in MDA-MB-231 cells blocked the effect of 3,6-DHF on increasing miR-34a mRNA and miR-34a promoter demethylation, suggesting that the increase of TET1 could be one of the mechanisms of breast cancer prevention by 3,6-DHF." (PMID 28870206, 2017). "Furthermore, it has been shown that the TET1 mediated DNA hydroxymethylation affects the expression of tissue inhibitors of metalloproteinases (TIMPs) in breast cancer, and the WNT pathway in colon cancer." (PMID 27014907, 2016). "Interestingly, overexpressing TET1 has been shown to activate TIMPs expression in breast cancer cells." (PMID 25977731, 2015). "In addition, TET1 depletion could impair the favorable effect of TSA (an inhibitor of histone deacetylases) in suppressing breast cancer invasion." (PMID 40014756, 2025).
breast cancer (continued). "Moreover, TET1 has at least two isoforms (long and short) that have distinct expression pattern and apparently different functions in tissue development and disease including breast cancer." (PMID 35646706, 2022). "In conclusion, our data suggest that TET1 isoforms have distinct expression pattern, localization and regulation in breast cancer and that long TET1 suppresses oncogenic phenotypes, and that further studies are necessary to elucidate the functional roles of different TET1 isoforms in breast cancer." (PMID 35646706, 2022). "Therefore, gain of methylation at the TET1 promoter may inactivate this gene and may play a significant role in multiple cancers including breast cancer." (PMID 34209564, 2021). "CircFECR1 enhances breast cancer (BC) invasion by recruiting ten–eleven translocation 1 (TET1) to the promoter of its parental gene Friend leukemia virus integration 1 (FLI1), inducing DNA demethylation and activating transcription." (PMID 33317550, 2020). "Therefore, we speculate that miR-29b promotes breast cancer cell proliferation and metastasis through regulation of the TET1 gene, which functions and coordinates several biological processes and pathways." (PMID 29254230, 2017). "However, in breast cancer, low expression of TET1 correlated with advanced cancer stage." (PMID 26366235, 2015). "At the same time, TET1 affects the expression of ADCY6 by removing DNA methylation, thereby regulating the malignant progression of breast cancer." (PMID 39823268, 2025). "In summary, our study elucidates the critical roles of GATA6 and TET1 in sustaining CAF function and driving breast cancer progression." (PMID 40216762, 2025). "Here, we identified the TET1/SMAD4/GATA6 regulatory axis as a central mechanism governing CAF transformation and function in breast cancer." (PMID 40216762, 2025). "Results showed that conditioned media from GATA6/TET1-depleted CAFs reduced migration and invasion of MDA-MB-231 breast cancer cells (p < 0.001 vs. Control 1)." (PMID 40216762, 2025). "In breast cancer cohorts (TCGA, METABRIC; n = 1,986), TET1 expression positively correlated with genes in the SMAD/TGF-β pathway, particularly SMAD4 (P < 0.05)." (PMID 40216762, 2025). "Knockdown of GATA6 or TET1 reduced CAF-mediated migration and invasion of breast cancer cells in vitro, while their overexpression enhanced cancer cell aggressiveness." (PMID 40216762, 2025). "To evaluate the role of GATA6 and TET1 in CAF-mediated tumor progression in vivo, we established a xenograft model using CFSE-labeled CAFs co-injected with breast cancer cells into nude mice." (PMID 40216762, 2025). "Sun et al32 discovered the high mobility group AT-hook 2 (HMGA2)–TET1–homeobox A9 (HOXA9) pathway, establishing it as a prognostic marker for breast cancer survival." (PMID 40520993, 2025). "The molecular constituents of FECR1/FLI1/TET1 employ a feedback loop to stimulate this through promoting DNA hypomethylation in the CpG islands of the promoter, ultimately controlling the metastasis of breast cancer (BC) cells." (PMID 39452835, 2024). "A study identified deletions in the TET1 gene and revealed that this gene was the most commonly deleted (8.6%) in metastatic TNBC tissue samples from The Metastatic Breast Cancer Project." (PMID 38203443, 2023). "Using lentiviral stable miRNA transfection together with cell biology functional assays and gene expression/target analysis, we investigated the interaction between miR-27a-3p, TET1 and ADCY6 in breast cancer." (PMID 35978806, 2022). "In order to study the function of at least the full TET1 enzyme in breast cancer, we infected breast cancer cell line MDA MB231 with viral particles either expressing HA-tagged full length TET1 (TET1-Lenti) or empty viral vector control (PSF-Lenti)." (PMID 35646706, 2022).
breast cancer (continued). "For the first time, this study demonstrates that TET1 increases the expression of ADCY6 through demethylation, and inhibits the progression of malignant biological behaviour of breast cancer by inhibiting EMT signaling pathway." (PMID 35978806, 2022). "In breast cancer, FECR1 circular RNA binds to the FLI1 promoter in cis and recruits TET1, reducing the DNA methylation of oncogenes, promoting their gene expression, and driving tumor metastasis through epigenetic mechanisms." (PMID 35978806, 2022). "miR-27a-3p negatively regulates the expression of TET1 and affects the EMT process of breast cancer through ADCY6, thereby promoting the malignant biological behaviour of breast cancer." (PMID 35978806, 2022). "In the same way, circFECR1 also downregulates DNMT1, an enzyme that is responsible for sustaining DNA demethylation during DNA replication, thereby regulating TET1 and DNMT1, and their subsequent effects are observed in breast cancer (BC) progression." (PMID 35223470, 2022). "Overall, these results demonstrated that miR-27a-3p binds to TET1 and downregulates TET1 to activate EMT by promoting DNA methylation of ADCY6, thus promoting proliferation, migration and invasion of breast cancer cells." (PMID 35978806, 2022). "More importantly, bioinformatics analysis showed that TET1 is regulated by miR-27a-3p and regulates the methylation of ADCY6 to affect the EMT process of breast cancer cells, thereby affecting the malignant biological behaviour of breast cancer." (PMID 35978806, 2022). "In breast cancer, when HMGA2 is depleted, an induction of the TET1 and HOXA9 genes occurs inhibiting invasion and metastization." (PMID 33375038, 2020). "Further study indicated that TET1 siRNA and pcDNA3/Myc-DNMT1 inhibited the 3,6-DHF reactivation effect on expression of miR-34a in breast cancer cells." (PMID 28870206, 2017). "TET1, a dioxygenase involved in cytosine demethylation, activates TIMP3 expression in breast cancer cells." (PMID 27058897, 2016). "Expression analysis of TET1 gene was performed on human T-cell acute lymphoblastic leukemia (T-ALL) cell lines (JURKAT, MOLT-3, SKW-3) and on cell lines of human breast cancer origin (MDA-MB-231, MCF7, T47D, MDA-MB-453)." (PMID 24939750, 2014). "SKW-3 and MDA-MB-453 showed the lowest TET1 expression out of T-ALL and breast cancer cell lines, respectively." (PMID 24939750, 2014). "For instance, TET1 and TET3 play a positive role in maintaining breast tumor-initiating cell phenotypes through the TET-TNFα-p38-MAPK axis, as evidenced by the CD44+/CD24− expression, a recognized biomarker of breast cancer stem cells." (PMID 40014756, 2025). "Furthermore, in breast cancer cell lines MCF-7 and MDA-MB-231, shRNA-mediated depletion of TET1 or TET3 would reduce the expression of mesenchymal genes N-cadherin and vimentin during hypoxia." (PMID 40764968, 2025). "Similarly, in basal-like breast cancer, it enhances invasion through POU4F1 activation, promoting cell cycle progression and invasion, whereas TET1 inhibition reduces metastatic potential." (PMID 41165593, 2025). "In breast cancer, uterine cancer, or glioblastoma, there is an enrichment of a truncated TET1 isoform that lacks the CXXC domain, thus presumably inhibit normal action of TET1." (PMID 39149518, 2024). "In the hormone-dependent breast cancer cell line (BT474), TET1 can suppress invasion and adhesion, whereas in triple-negative breast cancer cells (MDA-MB-231), TET1 acts in an opposite manner, promoting cell proliferation and migration via activation of the oncogenic PI3K–mTOR pathway." (PMID 39201247, 2024). "Breast cancer patients did not significantly differ from control group in terms of TET1, TET2, and TDG mRNA expression." (PMID 38499584, 2024). "In conclusion, our study demonstrates that TET1, which is negatively regulated by miR-27a-3p, functions as a key enzyme of DNA demethylation for ADCY6 and thereby leads to EMT and regulates malignant biological behaviour of breast cancer." (PMID 35978806, 2022).